S100A8 (S100 calcium binding protein A8)
Diseases named in the same sentence as S100A8 in open-access papers (continued):
Sharing a sentence is not in itself a finding about the gene and the disease.
Sepsis (continued). "Salivary levels for ITIH4 (Pig major acute phase protein, Pig-Map) and S100A8/A9 and S100A12 after stress, sepsis, and non-septic inflammation have been measured recently." (PMID 41199397, 2025). "The results show that S100A8 and S100A9 are important for the progression of sepsis, especially during the non-survivor phase, when they being strongly associated with inflammation and immune system dysregulation." (PMID 41303672, 2025). "More recently, a study conducted on plasma from patients with sepsis showed an increase in acetylated truncated S100A8 and S100A9 as well as monooxidized S100A8 in nonsurviving patients with septic shock." (PMID 33425215, 2020). "Plasma levels of S100A8 and S100A9 were elevated, as was up-regulation of S100A12, S100A9, and arginase-1 gene expression, in adults with sepsis, compared to non-septic patients in intensive care." (PMID 30555806, 2018). "Of note,administration of recombinant S100A8 and/or S100A9 at the onset of the late sepsis phasedid not impact sepsis outcomes in the S100A9 knockout mice." (PMID 29204146, 2017). "The levels of S100A8 and S100A9 were significantly elevated in the sepsis group without treatment." (PMID 32076015, 2020). "In vitro a significant reduction for IL-6, IFN-y, MIP-1α, C5a, HMGB-1, procalcitonin and S100-A8, but not of TNF-α could be achieved in blood samples with sepsis-like high cytokine levels by binding to CytoSorb® hemoadsorbent polystyrene beads." (PMID 33141843, 2020).
breast carcinoma (108 papers, 2005 to 2026). "Here, we show that S100A8/A9 innate immune signaling is a molecular mechanism that identifies smoking-related breast cancers and underlies their enhanced malignancy." (PMID 39856330, 2025). "We analyzed genetic data from breast cancer patients and identified a factor called S100A8/A9, which is linked to poor outcomes in early-stage cancer." (PMID 38378783, 2024). "Chronic stress and low social support in breast cancer patients are linked to increased inflammatory signaling and higher S100A8/S100A9 levels, connecting psychological factors with inflammation and metastasis." (PMID 39830522, 2024). "Elevation of S100A8 in the cancer cells and stroma is associated with poor prognosis in early-stage breast cancer patients." (PMID 36831371, 2023). "Amplification of S100A8 occurs in 10–30% of all breast cancers and has been linked to poorer prognosis." (PMID 37450087, 2023). "Collectively, high S100A8 level in serum was closely associated with clinicopathological features of breast cancer patients, predicting poor prognosis." (PMID 38093319, 2023). "Studies using human breast cancer cells in a xenograft model and confirmed with human clinical samples demonstrated that MDSCs produce S100A8 and are associated with poor survival and a shorter metastasis-free survival time." (PMID 36831371, 2023). "Aligned with our results, studies in breast cancer suggested that S100A8 is associated with tumor growth and invasion in breast cancer through the activation of the TLR4, RAGE, and NFκB pathways." (PMID 37174723, 2023). "In vitro and in vivo findings of S100A8/9 interaction with RAGE can cause human breast cancer, human prostate cancer, colon tumor, and oral and esophageal tumors." (PMID 36613714, 2022). "Using multiple cohorts data analyses, we have also found that a high S100A8 expression score was associated with higher stages (II/IV) and higher pathological grade (grade 3) of breast cancer patients." (PMID 34072157, 2021). "In conclusion, S100A8+ ICs seem to undergo a dynamic change during breast cancer progression in association with other IC subset infiltration." (PMID 33146829, 2021). "Further exploration using TCAGA-BRCA, SCAN-B, and METABRIC cohorts data analysis, revealed that a high S100A8 expression score was associated with the aggressive subtype TNBC or HER2+ breast cancers compared to the HR+ or HER2− breast cancer subtypes." (PMID 34072157, 2021). "Together, these results suggest that S100A8 is one of the important mediators associated with aggressive breast cancer metastasis and a prognostic factor for worse survival of breast cancer patients." (PMID 34072157, 2021). "In conclusion, infiltration of S100A8+ IC was associated with aggressive clinicopathological features and poor clinical outcome in our breast cancer patients." (PMID 33146829, 2021). "High S100A8 expression has been associated with increased disease specific and overall survival in both breast cancer and HNSCC33,34." (PMID 33469045, 2021). "S100A8+ ICs were already present in early stage of breast cancer and were associated with increased CD4+, CD8+, FOXP3+ TILs and PD-L + ICs infiltration." (PMID 33146829, 2021). "It was suggested that increased S100A8 expression at the protein level was associated with ER status in breast cancer patients, which was in agreement with the analysis from the online database." (PMID 30456203, 2018). "In this study, data from 140 breast cancer patients were retrospectively collected to examine the association between S100A8 expression and clinical prognosis." (PMID 30456203, 2018). "In conclusion, increased S100A8 protein expression was associated with poor survival and a higher probability of relapse in breast cancer patients." (PMID 30456203, 2018). "We revealed that the ER status of breast cancer patients had a close association with S100A8 protein expression." (PMID 30456203, 2018).
breast carcinoma (continued). "We also evaluated the association between the elevated expression of S100A8 and overall or relapse-free survival in breast cancer patients in online databases and showed similar results." (PMID 30456203, 2018). "To further investigate the association of HRD1 expression with breast cancer chemoresistance, we constructed S100A8 plasmid and chose the SiRNA of S100A8." (PMID 28423597, 2017). "The important role for S100A8/A9 in priming organs such as the brain and lung, for metastastic predisposition, has been demonstrated in murine breast cancer models." (PMID 28744322, 2017). "Together, suggest that high local or systemic IL-1β plus CXCL1 plus CCL2 plus S100A8 plus VEGF plus IL8 in breast cancer patients represents a diagnostic biomarker for the existence of IRISOE TNBC tumor, and propensity to reduced RFS, DMFS, or OS." (PMID 29262555, 2017). "In breast carcinoma, elevated levels of the S100A8 protein were associated with moderate/strong tumor inflammatory infiltration and significantly shorter DSS rates." (PMID 24885002, 2014). "In breast cancer, S100A8 and S100A9 are also linked with tumor progression being involved in regulating cancer cell behavior through extracellular and intracellular signaling pathways." (PMID 25298751, 2014). "Considering the association of high S100A12 and S100A8/A9 with worse prognosis in breast cancer and other types of cancer, this could be a contributing factor to the observed difference in survival in previous observational studies." (PMID 38468349, 2024). "Both S100A8/A9 and CA15-3 serum levels were considerably high in patients with breast cancer, and it was positively linked with tumor size, showing that the S100A8/A9 heterodimer might be regarded a possible biomarker for BRCA diagnosis and prognosis." (PMID 35646116, 2022). "It is reported that, S100A8 is associated with estrogen receptor loss in breast cancer." (PMID 28423597, 2017). "Additionally, S100a8 has been reported to increase the migration and proliferation of colorectal and pancreatic cancer cells in vitro and has also been associated with metastasis formation in breast cancer." (PMID 32493768, 2020). "While it is known that S100 A8 and A9 levels increase with skin aging, there is also a link to this protein’s expression in psoriasis and in breast cancer, where strong expression and secretion of S100A8/A9 may be associated with the loss of ERα in breast cancer." (PMID 28587197, 2017). "We also reported a crucial role of MCAM in breast cancer in response to extracellular S100A8/A9, underscoring the indispensable function of inflammatory cytokines in cancer-associated microenvironments." (PMID 40924339, 2025). "In turn, breast cancer cells increased S100A8/9 expression by myeloid cells, supporting breast cancer cell survival." (PMID 39863855, 2025). "Overexpression of S100A8 in breast cancer, ovarian cancer, liver cancer, acute myeloid leukemia, and melanoma, suggests its increased expression has been associated with tumor growth, invasion, and metastasis." (PMID 38361783, 2024). "Other authors found increased S100A8 gene and protein expression in breast cancer cells and the stroma of breast tumors." (PMID 39594999, 2024). "Since the S100 protein has been linked to breast cancer invasiveness and metastasis, the S100A8 and S100A9 appeared to reduce breast cancer malignancy by increasing mesenchymal to epithelial transitioning." (PMID 39594999, 2024). "Several DAMPs have been linked to postoperative immune suppression and infectious complications (High mobility group box 1 (HMGB1) and Heat shock protein 70 (HSP70)), and breast cancer (alarmins S100A8/A9 and S100A12)." (PMID 38468349, 2024). "S100A8/S100A9 high mRNA expression was correlated with lower OS in all breast cancer types, especially in Her2 positive and TNBC subtypes." (PMID 39830522, 2024).
breast carcinoma (continued). "The current study showed that S100A8 expression was greater in the A5 cell line compared to the A3 and T2 and correlated in certain aspects with clinical subtypes in breast cancer patients." (PMID 39594999, 2024). "Transcriptomic analysis of the MIND models again identified high expression of ERBB2 and Ki67 as risk factors, as well as additional factors such as S100A8/A9 and FOXD1, which are described to drive breast cancer proliferation." (PMID 37116492, 2023). "Using cBioPortal to explore the Molecular Taxonomy of Breast Cancer International Consortium (METABRIC) data set reveals that S100A8 is amplified in 21% of the tumors included therein." (PMID 37450087, 2023). "Survival analysis demonstrated that elevated S100A8/A9 predicted a poorer prognosis for breast cancer patients, and the mean expression of S100A8 and S100A9 independently served as a prognostic factor for overall survival in breast cancer patients." (PMID 38093319, 2023). "It has been demonstrated that S100A8 is altered in cervical, lung, anaplastic thyroid, and breast cancers." (PMID 37174723, 2023). "Pooled analyses were conducted to explore the relationships between S100A8/A9 mRNA level and clinicopathological features of breast cancer patients." (PMID 38093319, 2023). "In the present study, we considered LOX family proteins other than S100A8/A9 to clarify the significance of LOX family protein(s) in breast cancer progression, since their functions in breast cancer cells have not been fully elucidated." (PMID 37091157, 2023). "These neutrophils secreted S100A8/A9 cytokines to recruit circulating breast cancer TCs overexpressing the receptor of S100A8/A9." (PMID 37553342, 2023). "Consistently, in the present study, we verified that the N1-to-N2 chemoattractant ratio, such as the Cxcl1-to-S100a8 ratio, in the synthetic and endogenous MNs correlated with the aggressiveness of breast cancer and the disease progression." (PMID 37553342, 2023). "In our study, pooled analysis and immunohistochemical staining indicated that S100A8/A9 was upregulated at both mRNA and protein levels in breast cancer tissues." (PMID 38093319, 2023). "We examined S100A8 copy number (CN) alterations using fluorescence in situ hybridization in 475 primary breast cancers and 117 corresponding lymph nodes." (PMID 37450087, 2023). "At present, although S100A8/A9 has been reported to participate in breast cancer development, rare studies are exploring the prognostic value of S100A8/A9 in breast cancer." (PMID 38093319, 2023). "Our investigation involved an examination of the relationship between S100A8/A9 expression and various clinicopathological features of breast cancer." (PMID 38093319, 2023). "Diseased scaffolds and lungs in metastatic breast cancer models were abundant with S100A8/A9, and therefore both MNs recruited TCs with lung metastasis gene signature from the circulation." (PMID 37553342, 2023). "Considering the past and present findings together, we suggest that our developed S100A8/A9-mAb (Ab45) combined with the LOXL4-mAb will be more effective than any single inhibitor for the prevention of breast cancer outgrowth." (PMID 37091157, 2023). "In vitro experiments indicated that DACH1 overexpression reduced the production of S100A8 in breast cancer cells." (PMID 38093319, 2023). "S100A8/A9 protein in breast cancer samples was evaluated by immunohistochemistry staining with tumor tissue microarrays." (PMID 38093319, 2023). "S100A8/A9 is remarkedly increased in basal-like and Her2-overexpressed subtypes, predicting poor prognosis of breast cancer patients." (PMID 38093319, 2023). "This research aimed to delve deeper into the prognostic relevance of S100A8/A9 in the context of breast cancer." (PMID 38093319, 2023). "S100A8/A9 can mediate dynamic interaction between normal breast epithelial cells and adjacent breast cancer cells to induce reprogramming." (PMID 36624542, 2023).
breast carcinoma (continued). "We compared the values of the Cxcl1-to-S100a8 ratio in patients with grade 1, 2, or 3 breast cancers." (PMID 37553342, 2023). "Our efforts have revealed that S100A8/A9 induces the metastatic progression of breast cancer cells upon binding with an S100A8/A9 receptor, i.e., melanoma cell adhesion molecule (MCAM) on cancer cells." (PMID 37091157, 2023). "The multivariable analysis revealed that S100A8/A9 expression is an independent prognostic factor of OS for breast cancer patients (HR = 3.425, 95%CI 1.317–8.907) (P = 0.012)." (PMID 38093319, 2023). "The results showed that serum S100A8 concentration was higher in breast cancer patients, relative to patients with benign breast nodules (P = 0.002)." (PMID 38093319, 2023). "Collectively, S100A8/A9 is not only increased in breast cancers, but also further upregulated in poor differentiation, ER-, PR-, and Her2 + subtypes." (PMID 38093319, 2023). "Based on the public GEO database and online analysis tool Kaplan-Meier plotter, we interrogated the relationship between S100A8/A9 mRNA level and outcomes of breast cancer patients including OS, PFS, DMFS, and DFS." (PMID 38093319, 2023). "We found that S100A8 abundance is significantly higher in breast cancer tissue than normal breast tissue (P < 0.0001), breast inflammation (P = 0.0006), and hyperplasia breast tissue (P = 0.0130)." (PMID 38093319, 2023). "Previous studies have shown that recombinant human S100A8/A9 can reduce the cytotoxicity of doxorubicin/cyclophosphamide in breast cancer cells." (PMID 37701037, 2023). "In socially isolated animals, the herbal product inhibited IL6/JAK/STAT3 signaling, upregulated OXPHOS signaling, suppressed the expression of RAGE ligands S100a8 and S100a9, and prevented the increase in recurrence of dormant mammary tumors." (PMID 36980301, 2023). "S100A8 expression has only a marginal predictive effect in several malignancies, including breast cancer." (PMID 35646116, 2022). "A 2018 study reported an increased level of S100A8 expression levels in breast cancer patients with relapse and had significantly lower disease-free survival and overall survival durations." (PMID 35471994, 2022). "A study in breast cancer treatment found that cancer-associated endothelial cells contribute to the production of CXCL1/2 and S100A8/9, which eventually led to breast cancer cell survival and drug resistance." (PMID 36389798, 2022). "Breast cancer cell-derived CXCL1/2 recruits MDSCs to produce S100A8/9, thus augmenting the metastatic tendency of breast cancer cells." (PMID 36612163, 2022). "For the scenario 1 in the cohort 1 dataset, analysis of Normal vs. Breast Cancer samples produced model 1 which incorporated S100A8, S100A9, and breast density as the predictors." (PMID 36284356, 2022). "Analysis of Call-back vs. Breast Cancer samples produced model 2 which incorporated S100A8, S100A9, and age as the predictors." (PMID 36284356, 2022). "Analysis of Normal & Call-back vs. Breast Cancer samples produced a model 3 with S100A8 and S100A9 as the predictors." (PMID 36284356, 2022). "Up-regulation of S100A8/A9 occurs in various human cancer types including breast cancer, and both proteins are actively involved in tumor growth, metastasis, angiogenesis, and immune evasion in mouse models." (PMID 33523865, 2021). "The regulatory network TRIM24 was involved in showed that TRIM24, YAP1, Ifn, Ifnar, SOCS1, and S100A8 together activated atherogenesis and cell viability of breast cancer cell lines through 18 genes, including AKT1, ID2, etc.." (PMID 34575874, 2021). "In this study, we have shown for the first time the positive relationship between S100A8+ ICs and various IC subsets and their combined prognostic impact using human breast cancer tissues." (PMID 33146829, 2021). "Within the tumor microenvironment of breast cancer, S100A8 and S100A9 have both autocrine and paracrine functions." (PMID 33523865, 2021).